TNF (tumor necrosis factor)
Diseases named in the same sentence as TNF in open-access papers (continued):
Sharing a sentence is not in itself a finding about the gene and the disease.
Hyperinsulinemia (continued). "Autoimmune hypophysitis or elevated TNF-α levels could suppress ACTH secretion in the pituitary and, together with chronic exposure to IL-10, TGF-β1 and TNF-α and hyperinsulinemia could also suppress ACTH-stimulated cortisol secretion in the adrenal gland." (PMID 39044822, 2024). "Also, increased levels of TNF-α expression is strongly correlated with hyperinsulinemia and decreased insulin sensitivity." (PMID 37215099, 2023). "Moreover, the levels of TNF-α expression strongly correlate with hyperinsulinemia and decreased insulin sensitivity." (PMID 37215099, 2023). "TNF-α is secreted by fat tissue cells and TNF-α mRNA is associated with hyperinsulinemia." (PMID 37599681, 2023). "Interestingly, hyperinsulinemia induces the increase in inflammatory cytokines, IL-6 and TNF-α, thereby promoting IR." (PMID 35795140, 2022). "TNF-α can not only damage vascular endothelial cells directly but also induce hyperinsulinemia." (PMID 35216583, 2022). "Furthermore, hyperinsulinemia increases plasma and cerebrospinal fluid (CSF) concentrations of interleukin-6 and tumor necrosis factor alpha." (PMID 32726329, 2020). "Various pathobiological factors, including proinflammatory cytokines (such as interleukin (IL)-6 and tumor necrosis factor (TNF)-α), leptin, hyperinsulinemia, the gut microbiota, bile acid, and free fatty acid, can interact with components in the liver microenvironment." (PMID 32770081, 2020). "In addition, IL6, IL1B1 and TNF are associated with increased susceptibility to PCOS, and INSR plays a role in compensatory hyperinsulinemia." (PMID 30181771, 2018). "Hyperinsulinemia promotes TNFα production in migrated macrophages." (PMID 30114249, 2018). "In this context, we propose to study new molecular mechanisms that help to explain whether the moderate hyperinsulinemia or lowering TNF-α levels might have a protective role against vascular damage mediated by UCP-2 expression levels." (PMID 25077985, 2014). "Additionally, hyperinsulinemia augments TNFα-stimulated VCAM-1 expression above that seen for TNFα alone." (PMID 22093181, 2011). "Increased adiposity and hyperinsulinemia has been closely linked to low-grade systemic inflammation in the course of EMS, resulting from the excessive production and release of various adipokines including the proinflammatory cytokines IL-1, IL-6, and the tumor necrosis factor (TNF) α." (PMID 38146533, 2023). "Therefore, we hypothesize that TNF-α is a potential inducer to deteriorate hyperinsulinemia and subsequent T2DM by promoting β cell mass and insulin secretion." (PMID 35198097, 2022). "With respect to TNF‐α, systemic factors, that is, hyperinsulinemia, might trigger the increased arterial presence of this pro‐inflammatory cytokine in 6‐month‐old Cc1−/− mice as suggested, since we were unable to detect TNF‐α in our cultured endothelial cells under basal conditions." (PMID 31389127, 2019). "It is the upregulation of proinflammatory mediators, that is, TNF-α and leptin, and the downregulation of anti-inflammatory molecules, that is, adiponectin, that lead to the development of chronic inflammatory state and contribute to the hyperinsulinemia in GDM." (PMID 25202741, 2014). "To get a new insight on that UCP-2 protective effect on the vasculature, we have studied new molecular mechanisms that help to explain whether the moderate hyperinsulinemia or reduction TNF-α levels might have a protective role against vascular damage mediated by UCP-2 modulation." (PMID 25077985, 2014). "Also, a direct relationship between elevation of TNF-α and hyperinsulinemia has been reported." (PMID 24481132, 2014). "Elevated expression of TNF-α, MCP-1, or IL-6 has been further reported to significantly reduce the expression of GLUT4 and promote the compensatory hyperinsulinemia." (PMID 38146533, 2023). "HFD-fed CadKO males showed reduced proinflammatory adipocytokines (TNFα, IL1β, IL6), thus reducing inflammation, macrophage infiltration, and hyperinsulinemia." (PMID 37443781, 2023).
Hyperinsulinemia (continued). "In T2DM, overweight patients are not only high serum free fatty acids and hyperinsulinemia, but also increased leptin, MCP-1, IL-6, and TNF-α production by adipocytes." (PMID 34003397, 2021). "Inflammatory stimuli, such as IL-6, TNFα, and endotoxin, induce GIP and GLP-1 secretion, leading to hyperinsulinemia in critically ill patients." (PMID 31126070, 2019). "Enlarged adipocytes in response to hyperinsulinemia release inflammatory cytokines such as MCP-1 and TNFα, leading to inflammatory monocytic infiltration of the WAT32." (PMID 30451856, 2018). "Hyperinsulinemia and a perturbed PI3K pathway appear to augment TNFα stimulation of VCAM-1 protein, VCAM-1 translocation to the cell surface and nuclear import of NFκB." (PMID 22093181, 2011). "Hyperinsulinemia can decrease ACTH secretion and, together with chronic exposure to IL-10, TGF-β1 and TNFα could also decrease cortisol secretion." (PMID 37718435, 2023). "In the hyperinsulinemia/euglycemic clamp model of EL, the cohort of genes examined included few downstream targets of IL-17A activation, but these studies identified both MMP9 and TNFα upregulation." (PMID 33301461, 2020). "Similarly, subjects with severe hyperinsulinemia, hypertriglyceridemia, high body mass index, and low HDL-cholesterol were reported to have high circulating TNF-α levels." (PMID 30114249, 2018). "Compared to a reference bottlenose dolphin without metabolic perturbations, the current study identified activated cytokine gene expression, including TGF-β, TNF-α, IFN-γ, IL-18, IL-13, IL-10, and IL-4 in the liver or spleen of a geriatric bottlenose dolphin with hyperinsulinemia." (PMID 24101915, 2013). "Rosiglitazone treatment reduced hyperinsulinemia (DIO 4510 +/− 490 pg/ml: DIO-Rosi 2170 +/− 620 pg/ml), serum CCL2 levels (DIO 84.2 +/− 0.18 pg/ml: DIO-Rosi 47.3 +/− 4.6 pg/ml) and SVF mediator production of IL-6, TNFα, IL-1β and IL-10." (PMID 20445733, 2010). "Hyperinsulinemia dysregulates the endocrine activity of hypertrophied adipocytes by stimulating the production of non-esterified fatty acids, which increase the secretion of tumor necrosis factor α (TNFα) by the adipocytes." (PMID 40141439, 2025). "An in vivo study showed that insulin concentration (10−9–10−7 mol/L) induced VCAM-1 expression and markedly increased TNF-α via NF-kB activation and IkB-α accumulation, so we suspect that hyperinsulinemia stimulates the expression of VCAM-1, not the blood pressure." (PMID 37822716, 2023). "Inflammatory cytokines produced by the adipose tissue, such as TNF-α (tumor necrosis factor-α) and interleukin-6 (IL-6) have been related to reduce GLUT4 expression, consequently lowering glucose uptake by muscle, and participating on the compensatory hyperinsulinemia." (PMID 22897936, 2012). "This study was performed in order to determine whether or not hyperinsulinemia increases the effects of TNFα-stimulated expression of VCAM-1 above that seen for TNFα alone and which molecular pathways in particular mediate this effect." (PMID 22093181, 2011). "In contrast to the lack of correlation with serum leptin, TNF-α, IL-6, NF-κB and STAT3 activation, hyperinsulinemia in the foz/foz model remained a candidate enhancer of hepatocarcinogenesis." (PMID 30873458, 2016). "In our study, 8-week HF feeding to mice induced mild body weight gain (14.4% or 3.7 g), increased FBG level within the normal range (< 126 mg/dL), and upregulated levels of a part of serum cytokines (TNF-α and IL-10) and lipids (TC and HDLC) without hyperinsulinemia." (PMID 30719451, 2019). "The down-regulation of TLR4 combined with the lack of increased production of pro-inflammatory cytokines (i.e., IL-6 and TNF-α) and SOCS3 following insulin infusion in the current study suggested that hyperinsulinemia exerts an anti-inflammatory effect on the heart in non-obese individuals." (PMID 25101057, 2014).
liver cancer (147 papers, 2012 to 2025). An epithelial or non-epithelial malignant neoplasm that arises from the liver. "Chronic inflammation, a known risk factor for liver cancer, was supported by elevated IL-6 and TNF-α protein levels in mouse serum." (PMID 39056720, 2024). "NF-κB inhibition through anti-TNF treatment resulted in apoptosis of transformed hepatocytes and failure to progress to HCC, indicating that TNF-induced NF-κB activation is essential for promoting inflammation-associated liver cancer." (PMID 33917839, 2021). "Consistently, the potentiation of cell death induced in liver cancer cell cultures by the combined treatment with taxol and TNFα was associated with reduced levels of both phosphorylated STAT3 and SOCS3, one of the STAT3 target genes." (PMID 31653043, 2019). "A genome-wide association study has noted a direct link of single nucleotide polymorphisms at the ABO locus to serum levels of tumor necrosis factor-alpha, an inflammatory cytokine known to modulate risk of liver cancer." (PMID 28880901, 2017). "The expression of AFP in liver cancer is associated with cell proliferation, angiogenesis, and increased resistance of cells against tumor necrosis factor-related apoptosis." (PMID 25738614, 2015). "The medicine may diminish inflammatory cytokine cascades (e.g., TNF-α, IL-6) by reducing glucose levels and enhancing insulin sensitivity, so mitigating liver damage and fibrosis, which elevate the risk of liver cancer." (PMID 40439888, 2025). "Therefore, elevated levels of these inflammatory markers (i.e. IL-1β, IL-4, IL-6, IL-10, TNF-α and C-reactive protein) increase the risk of liver cancer development." (PMID 37990536, 2023). "Notably, the TNFα levels could be directly associated with improved survival rates, which have been shown to display an inverse association with TNFα inhibition and deletion in a rat liver cancer model constructed by DEN treatment." (PMID 34829862, 2021). "RNA sequencing analysis revealed significant enrichment of the TNF-α signaling pathway in liver cancer cell lines treated with Y-A." (PMID 39056720, 2024). "Kupffer cells and inflammatory monocytes also play a role in promoting the transition from chronic hepatitis to liver cancer by releasing proinflammatory cytokines such as TNFα, IL-6, and monocyte chemoattractant protein 1 (MCP-1)." (PMID 39000296, 2024). "The study identified AKT1, EGFR, ALB, and TNF genes as potential therapeutic targets against hepatic cancer." (PMID 39502516, 2024). "AIF1 induction by TNF-α stimulation promotes macrophage recruitment and liver inflammation, affecting the liver microenvironment and potentially contributing to liver cancer development." (PMID 39254691, 2024). "Experimental findings suggested that complete inhibition or ablation of TNF-α attenuates liver cancer progression in laboratory mice." (PMID 38553531, 2024). "Simultaneously, research has demonstrated that ERS is induced by MC-LR in liver cancer cells, as well as the NF-κB and TNFα signaling pathways, leading to the hepatotoxicity, inflammation, and carcinogenic effects." (PMID 39273011, 2024). "CHI3L1 promotes an inflammatory response in liver cancer cells by activating signaling pathways that induce the production of proinflammatory cytokines, such as IL-6 and TNF-α." (PMID 38177294, 2024). "TNF-α is an important factor involved in the pro-inflammatory response, which can promote tumor growth and poor prognosis of liver cancer." (PMID 37033618, 2023). "Our findings illustrate that PD-L1 Iso2 can increase the number of T cells in the tumor microenvironment by elevating TNF levels, which is a necessary part of the tumor-suppressive effects of Iso1 in liver cancer." (PMID 37047287, 2023).
liver cancer (continued). "The liver cancer cell line Hep3B, when treated with apigetrin, exhibited TNFα-induced apoptosis and necroptosis through ROS generation." (PMID 37509167, 2023). "In conclusion, our findings highlight that PD-L1 Iso2 can increase the number of T cells in the tumor microenvironment by elevating TNF levels, which is required for the tumor-suppressive effects of Iso1 in liver cancer." (PMID 37047287, 2023). "Similar results were confirmed in the Mongolian liver cancer cohort, and the Iso2/TNF/T-cell axis was verified in several other cancers in the TCGA cohort." (PMID 37047287, 2023). "Taken together, our results confirm that Iso2 can directly upregulate TNF synthesis in tumor cells, thus increasing T cell numbers in the tumor microenvironment of liver cancer." (PMID 37047287, 2023). "According to the results of GO and KEGG enrichment analysis, the targets of HDW's antiangiogenic effect in liver cancer are primarily involved in signalling pathways such as TNF-α and IL-17." (PMID 36647454, 2023). "In our study, we found that the knockdown of IQGAP1 induces the production of pro-inflammatory cytokines that were otherwise suppressed by the DENA-induced liver cancer, through the activation of TNF-α and interleukins." (PMID 36276098, 2022). "Here, we established a model of inflammatory-induced liver cancer by treating Hepa1-6 cells and Huh7 cells with TNF-α." (PMID 35676936, 2022). "We previously reported that metformin also reduces the number of TNFα+ cells in zebrafish liver cancer models." (PMID 35200139, 2022). "All of the obtained compounds were tested in a JNK1 enzymatic inhibition assay and in a cell-based assay by measuring the inhibition of the TNFα (tumor necrosis factor)-stimulated phosphorylation of c-Jun in HepG2 (human liver cancer) cells." (PMID 35566124, 2022). "For example, in pancreatic and liver cancers under irradiation, fibroblasts increase the secretion of various humoral factors including cytokines such as bFGF, TNF-a, VEGF, IL-6, EGF, MMP-2, and MMP-9." (PMID 35089951, 2022). "It decreased the levels of liver dysfunction biomarkers (SGPT and SGOT), lipid peroxidation (LPO), and stimulated SIRT1 to inhibit NF-κB, thereby increasing the sensitivity of liver cancer cells to TNF-α-induced apoptosis." (PMID 36278230, 2022). "At the same time, the content of IL-1α, IL-12 P70, TNF α, IL-1β and IL-6 was significantly reduced, and the content of IL-10 was significantly increased like in the previous liver cancer model." (PMID 34976592, 2022). "It broadens our understanding of the pharmacological roles of PNG and GsRb1 on TNF-α-induced chronic inflammation in cardiac cells and hepatic cancer cells." (PMID 36432152, 2022). "Two different concentrations (20 μg/ml and 40 μg/ml) of Tribulusterrestris methanolic plant extract were subjected to assess the protein concentration of TNF-α and IL-1β through ELISA in the HepG-2 liver cancer cell line." (PMID 36577761, 2022). "Taken together, these cytokines are pro-tumorigenic in the liver, and both TNF- and LT-mediated signaling contribute to liver inflammation, determining their ability to induce and promote liver cancer progression." (PMID 33917839, 2021). "MANF is located in the nucleus and co-localises with liver cancer cells treated with p65 and tumour necrosis factor-α (TNF-α) in liver cancer tissues." (PMID 34830854, 2021). "A recent study revealed that MASTL promotes proliferation and mitotic entry of human liver cancer cells upon induction of proinflammatory cytokines (i.e., IL-6, TNF (tumor necrosis factor)-alpha)." (PMID 31947935, 2020). "Zebrafish skin and liver cancer models showed an upregulation of the pro-inflammatory cytokines IL-1β and TNFα in response to tumour initiation." (PMID 32325966, 2020). "There are also many studies that showed the strong relationship between TNF-α and the development of liver cancer." (PMID 31781194, 2019).
liver cancer (continued). "After liver damage occurs, hepatic macrophages secrete pro-inflammatory cytokines and chemokines, including IL-1β and TNF, activating the inflammation-tumorigenesis cascade and triggering the immune escape that fuels the development of liver cancer." (PMID 31523179, 2019). "Researches showed that serum level TNF-α, IL-lα and IL-1β in liver cancer patients were significantly higher, especially higher in patients with recurrence of liver cancer." (PMID 31341840, 2019). "MyD88 signaling induces translocation of NF-κB to the nucleus and the transcription of cytokines such as IL-6 and TNF-α that are essential for the initiation of DEN-induced liver cancer." (PMID 31049358, 2019). "TNF-α promotes blood vessel growth and promotes tumor progression and metastasis, and TNF-α can be used to predict the occurrence and recurrence of liver cancer." (PMID 31832112, 2019). "The results reported in the present study show for the first time that also the cytotoxic effect exerted in liver cancer cell lines by EVOO extract can be potentiated by TNFα, otherwise ineffective." (PMID 31653043, 2019). "Group II genes, which were highly expressed in both types of Huh7 spheroids as compared to human liver cancer tissues, were related to cytokine-related signalling, including TNF and MAPK signalling." (PMID 28874716, 2017). "A higher state of inflammation was observed in liver cancer tissues as evident from upregulation of inflammatory cytokines IL-6 and TNF-α along with NF-κB and STAT3." (PMID 27760163, 2016). "In this direction, we examined the expression of inflammatory proteins IL6, STAT3, TNF-α and NF-κB in hepatic cancer tissues." (PMID 27760163, 2016). "It has been suggested that TNF-α plays an important role in the progress of different types of cancer including liver cancer." (PMID 25197311, 2014). "The suppression of HOTAIR in liver cancer cells reduces cell viability and invasion, sensitizes the cells to TNF-induced apoptosis and increases chemotherapeutic sensitivity." (PMID 23717443, 2013). "Our data demonstrate that APE1 overexpression does not protect from FAs induced cell damage and that APE1 and NF-κB play an essential role in TNF-α-induced transcriptional activation of IL-8 gene expression in hepatic cancer cell lines." (PMID 23967134, 2013). "In this study, we demonstrated that in JHH6 hepatic cancer cells, E3330 treatment inhibits TNF-α-induced IL8 production through impairment of APE1 subcellular distribution, thus confirming a novel aspect of E3330 effect on APE1 modulation." (PMID 23967134, 2013). "In conclusion, we demonstrate that HBx deregulates TSC1/mTOR signaling through IKKβ and renders liver cancer cells more sensitive to TNF-α stimulation in activating mTOR downstream S6K1 activity through IKKβ signaling." (PMID 22848663, 2012). "Selective TNF-targeting of primary and secondary tumors of the liver by transient and specific depletion of hepatocytic ATP opens up a new clinical avenue for the TNF-based treatment of liver cancers." (PMID 23272249, 2012). "Meanwhile, the role of TNF-α can be seen in many human malignancies, including breast, gastric, pancreatic, ovaries, endometrial, prostate, bladder, colorectal, oral and liver cancer." (PMID 39911325, 2025). "Moreover, TNF is capable of activating growth signals by means of cytokines, consequently affecting liver cancer invasion." (PMID 39544939, 2024). "Kupffer cells and inflammatory monocytes promote the transition from chronic hepatitis to liver cancer by releasing proinflammatory cytokines such as TNFα, IL-6, and MCP-1, and inducing CD8+ T-cell exhaustion in collaboration with myeloid-derived suppressor cells (MDSCs)." (PMID 39000296, 2024). "Moreover, another study found that CHI3L1 increased the TNF-α-induced proliferation, migration, and invasion of liver cancer cells." (PMID 38177294, 2024).